CLCA1 (chloride channel accessory 1)
Diseases named in the same sentence as CLCA1 in open-access papers (continued):
Sharing a sentence is not in itself a finding about the gene and the disease.
pancreatic cancer (2 papers, 2016 to 2018). "The aim of the study was to further validate the prognostic significance of CLCA1 in pancreatic cancer." (PMID 30419838, 2018). "In a previous study utilizing mass spectrometry-based proteomics, we identified calcium-activated chloride channel regulator 1 (CLCA1) as a potential tumor suppressor in pancreatic cancer and the expression was inversely correlated with patient survival." (PMID 30419838, 2018). "However, we noted that CLCA1 was present in more than half of pancreatic cancer tissues in our study." (PMID 30419838, 2018). "Low CLCA1 expression is an independent factor of poor disease-free survival in pancreatic cancer." (PMID 30419838, 2018).
pancreatic ductal adenocarcinoma (2 papers, 2018 to 2022). An infiltrating adenocarcinoma that arises from the epithelial cells of the pancreas. "CLCA1 expression was evaluated with tissue microarrays and immunohistochemistry in 140 patients with pancreatic ductal adenocarcinoma that underwent surgical resection at Skåne University Hospital, Sweden." (PMID 30419838, 2018).
Pneumocystis infection (2 papers, 2014 to 2019). "Increased expression of goblet-cell-derived CLCA1 protein plus excess mucus in infant autopsy lungs and in murine models of primary Pneumocystis infection alert of innate immune system immunopathology associated to Pneumocystis infection." (PMID 31333624, 2019). "Induction of the CLCA1 pathway with increased mucins has been shown to correlate with Pneumocystis infection in humans and in animal models and is strongly related to IL-13 driven mucus cell metaplasia, STAT6 activation and MUC5AC and MUC5B expression in the airways." (PMID 31333624, 2019).
chronic kidney disease (1 paper, 2025). Impairment of the renal function secondary to chronic kidney damage persisting for three or more months. "Interrogation of published gene expression data in kidney biopsies of humans showed that chronic kidney diseases of diverse etiology are associated with increased expression of CLCA1 and TMEM16A." (PMID 39782685, 2025).
cocaine addiction (1 paper, 2020). "Twelve DEGs (Myct1, Gm21860, Ninj2, Fam183b, Lars2, Alkbh1, Fgf5, Frmd7, Tm6sf2, Wnt6, Batf3, and Clca1) were found to be regulated inversely among the overlap genes, which may be possible targets of RPA to disrupt the cocaine addiction process." (PMID 32489401, 2020).
colon adenocarcinoma (1 paper, 2025). "Chloride channel accessory 1 (CLCA1) is considered a potential prognostic biomarker for colon adenocarcinoma (COAD)." (PMID 40690457, 2025).
colorectal adenocarcinoma (1 paper, 2022). The most common type of colorectal carcinoma. "In conclusion, by integrating WGCNA and differential gene expression analysis, our study screened five important survival-related genes (SLC26A3, GUCA2A, CLCA4, CLCA1, and AQP8) and a 3-gene risk model with the potential to predict the prognosis of colorectal adenocarcinoma." (PMID 35693937, 2022).
colorectal adenoma (1 paper, 2021). An adenoma that arises from the colon or rectum. "In summary, this study identified a set of differentially expressed genes in CRC, including FcGBP, CLCA1, ADH1C, COL1A1, ZG16, which could be strong candidates to be used as biomarkers of colorectal adenoma-adenocarcinoma progression." (PMID 33648461, 2021).
colorectal tumours (1 paper, 2010). "In contrast, the expression of two other chloride channels (the Ca2+-dependent chloride channels CLCA1 and CLCA2) was downregulated in 80% of colorectal tumours, although the biological significance of this repression remains to be determined." (PMID 20087350, 2010).
cyst (1 paper, 2018). A sac-like closed membranous structure that may be empty or contain fluid or amorphous material. "Indeed, CLCA1 has been proposed as a supportive marker for high-grade dysplasia and malignant transformation using cyst fluid samples." (PMID 30419838, 2018).
diabetes (1 paper, 2025). "Thus, in diabetes, signals from increased Cl– secretion by the CLCA1/TMEM16A system lead to activation of mTORC1, resulting in increased synthesis of proteins, including matrix proteins." (PMID 39782685, 2025). "Our investigation shows the following: (a) Diabetes is associated with increase in the kidney expression of CLCA1 and TMEM16A, resulting in increased Cl– current; (b) CLCA1/TMEM16A/Cl– current system participates in stimulation of mTOR and increased matrix protein expression." (PMID 39782685, 2025). "Mechanisms by which diabetes regulates renal CLCA1 and TMEM16A expression in mice are distinct." (PMID 39782685, 2025). "Among participants with diabetes there was a positive correlation between tubular TMEM16A expression (but not CLCA1) and urinary albumin-to-creatinine ratio (r value 0.39, P = 0.0059)." (PMID 39782685, 2025). "Renal cortical expression of CLCA1 and TMEM16A is increased in diabetes." (PMID 39782685, 2025).
enteropathy (1 paper, 2021). "The enteropathy was associated with an extensive depletion of goblet cells indicated not only by H&E but also by the more sensitive staining of TFF3, CLCA1, and processed and unprocessed MUC2." (PMID 34237462, 2021).
Familial adenomatous polyposis (1 paper, 2021). Familial adenomatous polyposis (FAP) is characterized by the development of hundreds to thousands of adenomas in the rectum and colon during the second decade of life. "CLCA1 and ADH1C were shown to be downregulated in familial adenomatous polyposis." (PMID 33648461, 2021).
intestinal obstruction (1 paper, 2012). Blockage of the normal flow of the intestinal contents within the bowel. "Evidence of association between MI and the p.Ser357Asn variant in CLCA1, the human ortholog of the murine Clca3, in 682 European CF subjects suggests that this goblet cell marker may also contribute to intestinal obstruction in humans." (PMID 22438829, 2012).
liver cancer (1 paper, 2025). An epithelial or non-epithelial malignant neoplasm that arises from the liver. "Reduced CLCA1 expression in tumors has been significantly linked to poor outcomes in several human cancers, such as colorectal, ovarian, pancreatic, and liver cancers." (PMID 40690457, 2025).
lung diseases (1 paper, 2021). "Expression of CLCA1 is particularly enhanced in goblet cell metaplasia and is associated with various lung diseases." (PMID 34066250, 2021). "Expression of CLCA1 is enhanced in goblet cell metaplasia and associated with various lung diseases." (PMID 34066250, 2021).
metastatic colorectal cancer (1 paper, 2015). "Affinity purification using the lectin HPA followed by proteomic analysis revealed annexin 4, annexin 5 and CLCA1 to be increased in the metastatic colorectal cancer specimens." (PMID 26495974, 2015).
obstructive chronic bronchitis (1 paper, 2012). "Although the participation of IL-13 and other Th2 cytokines in COPD, including chronic bronchitis, has also been reported in several studies, they may be not important contributors to CLCA1 expression in COPD." (PMID 22731784, 2012).
Pancreatic cysts (1 paper, 2018). A cyst of the pancreas that possess a lining of mucous epithelium. "It is worth mentioning that CLCA1 can be secreted into pancreatic cyst fluid and the blood stream, which makes the CLCA1 a possible serum and fluid biomarker for PDAC." (PMID 30419838, 2018).
type 2 diabetes (1 paper, 2025). "In mice with type 2 diabetes, renal cortical CLCA1 and TMEM16A content was increased." (PMID 39782685, 2025).
tumor (38 papers, 2011 to 2026). "CLCA1, closely linked to mucin production, can significantly alter the tumor microenvironment, affecting cell adhesion and migration." (PMID 39910169, 2025). "Reduced expression of CLCA1 may cause “damage to the intestinal mucosal barrier,” increasing local inflammation and attracting immunosuppressive cells, which can facilitate tumor development." (PMID 41602387, 2026). "CLCA1, a chloride channel protein, might be linked to tumor growth and spread." (PMID 37702857, 2023). "CLCA1, a tumor suppressor, inhibits CRC progression by suppressing Wnt/β-catenin signaling and EMT, consistent with its reduced expression in advanced tumors and inverse correlation with metastasis." (PMID 40145096, 2025). "To begin, CLCA1 expression levels were analyzed between healthy and tumor tissues across 33 human tumor types." (PMID 40690457, 2025). "In vitro studies suggest that CLCA1 can act as a tumor suppressor in COAD by hindering the Wnt/beta-catenin signaling pathway and preventing epithelial-mesenchymal transition (EMT)." (PMID 40690457, 2025). "The differential analysis revealed the downregulation of CLCA1 expression in tumor tissues from multiple tumors, including COAD." (PMID 40690457, 2025). "The tumour-suppressive function of CLCA1 is based on inhibition of EMT and the Wnt/β-catenin signalling pathway: both pathways reduce proliferation but promote differentiation, migration, and invasion." (PMID 36691026, 2023). "After the measurement of tumour size, the solid tumour tissue was fixed in formalin solution to detect the expressions of CLCA1, UGT2A3 and B3GNT6." (PMID 36855796, 2023). "Seven hub genes, REG4, S100A7, CLCA1, FABP4, RETNLB, SFRP2, and WNT10A, were all significantly associated with CC patient prognosis and differentially expressed in normal and tumor tissues." (PMID 36941538, 2023). "In vitro and in vivo results of this study suggested that CLCA1 plays a key role as a tumor suppressor in CRC by suppressing the epithelial–mesenchymal transition (EMT) and Wnt/beta-catenin signaling pathway." (PMID 35907803, 2022). "CLCA1 has a tumor suppressor role by inhibiting the Wnt/beta-catenin signaling pathway and the EMT process." (PMID 35194111, 2022). "Consistent of previous results, expression level of CLCA1 was lower in tumor relative to adjacent tissues." (PMID 34217290, 2021). "To further explore its characteristics, we analyzed differences in CLCA1 expression levels between tumor and normal tissues, across clinical stages, and across TNM stages." (PMID 33251137, 2020). "The results of gene set enrichment analysis (GSEA) and immune infiltration analysis showed that CLCA1 was closely related to tumor metabolism and immune invasion of CRC." (PMID 33251137, 2020). "Similar results as described in this murine model system were recently reported in the context of studies focusing on CRC patients and thus Clca1 is currently discussed to have tumor-suppressive properties." (PMID 29416634, 2018). "CLCA1 expression was denoted as positive in 90 tumors (64.3%), with positive staining being limited to the tumor cells." (PMID 30419838, 2018). "In our study, the increased expression of CLCA1 reduced the beta-catenin expression level and repressed EMT, which probably explains the tumor-inhibitory activity of CLCA1." (PMID 28974231, 2017). "CLCA1 functions as a tumor suppressor possibly via inhibition of the Wnt/beta-catenin signaling pathway and the EMT process." (PMID 28974231, 2017). "A six-fold increase in mRNA expression was observed in tumor samples of CL, CLCA1 and CLCA2 groups relative to the NC group." (PMID 21811552, 2011). "The tumor volumes of CL, CLCA1, and CLCA2 groups were similar and all animals were able to eliminate the tumors." (PMID 21811552, 2011).
tumor (continued). "A notable finding of this study is that CLCA1, UGT2A3, and ZG16—three genes highly expressed in normal colorectal tissues—are consistently downregulated in tumor tissues, suggesting that their loss may represent a coordinated event in CRC progression." (PMID 41602387, 2026). "CLCA1 may function as a tumor suppressor by inhibiting the Wnt/β-catenin signaling pathway and the epithelial-mesenchymal transition (EMT) process." (PMID 38612764, 2024). "Expression level of CLCA1 between normal tissues and tumor samples was compared based on TCGA data." (PMID 34217290, 2021). "Relative to tumor tissues, CLCA1 was upregulated in adjacent normal specimens." (PMID 34217290, 2021). "Furthermore, the Clca1 expression level seems to be of prognostic value since the OS of CRC patients was significantly improved in patients with high tumor-resident Clca1 expression." (PMID 29416634, 2018). "In particular, Clca1, a protein secreted by goblet cells and known to be involved in the regulation of cell proliferation and differentiation shows a strong down-regulation in tumor samples versus normal tissues." (PMID 29416634, 2018). "In addition, CLCA1 functions as a tumor suppressor possibly by downregulating the Wnt/beta-catenin signaling pathway and EMT." (PMID 28974231, 2017). "In Yap1KD; Gp130FF tumor organoids, we found reduced transcript levels for Igsf9 (marker for cell proliferation), Cyp2c65, (lipid and glucose metabolism), Ptgr1 and Sult1c2 (metabolite biosynthesis), and Clca1 (mucosal defence) when compared with Yap1WT; Gp130FF tumor." (PMID 37957015, 2024). "Therefore, we hypothesize that the tumor-suppressor function of CLCA1 might be related to TMEM16A stabilization and thus reduce its tumor promotion ability, which needs further investigation." (PMID 28974231, 2017). "We identified three key genes—CLCA1, UGT2A3, and ZG16—and found that they all were downregulated in tumor tissues across the TCGA-COAD and GEO datasets, as well as in independent clinical samples." (PMID 41602387, 2026). "Normal tissues showed significantly higher relative expression of CLCA1, UGT2A3, and ZG16 compared with tumor tissues." (PMID 41602387, 2026). "Contrary to expectations, knockout of CLCA1 via CRISPR technology led to enhanced proliferation and metastasis of tumor cells, indicating that high expression of CLCA1 suppresses Wnt signaling and the EMT process, thereby inhibiting tumor growth." (PMID 39370455, 2024). "According to the HPA database, the protein levels of SLC26A3, GUCA2A, CLCA4, CLCA1, and AQP8 in tumor tissues were all significantly lower than that in normal tissues." (PMID 35693937, 2022). "As expected, the tumor cells tended to show lower expression of differentiation genes such as enterocyte markers (CA1, CA2, and CLCA1) and endocrine cell markers (PYY and GCG)." (PMID 35974387, 2022). "CLCA1 decreased expression was also described in serum and CRC tissues, showing an inverse correlation with CRC metastasis and tumor stage." (PMID 33648461, 2021). "Furthermore, CLCA1 might serve as opposing role in progression of tumor." (PMID 34217290, 2021). "Therefore, the role of CLCA1 in tumor progression may depend on the types of tumors." (PMID 31871532, 2019). "All the tumor biopsies of animals inoculated with ACP03 (CL, CLCA1 and CLCA2 groups) presented MYC protein overexpression." (PMID 21811552, 2011). "Furthermore, three genes (CLCA1, UGT2A3, and ZG16) were significantly downregulated in tumor tissues." (PMID 41602387, 2026). "Although panomics revealed low RNA and protein expression of CA1, CLCA1, MATN2, AHCYL2, and FCGBP in malignant tissues compared to healthy colon mucosa, no differentially expressed RNA or protein targets were detected between tumour and metastatic tissues." (PMID 36691026, 2023). "Both CLCA1 and CLCA4 are expressed in the intestine, may act as tumor suppressors, and are negatively correlated with tumor formation." (PMID 35693937, 2022).
tumor (continued). "In addition, CLCA1 serum concentration and mRNA expression level in CRC tissues were inversely correlated with CRC metastasis and tumor stage." (PMID 28974231, 2017). "In addition, the CLCA1 serum concentration and CLCA1 mRNA expression level were inversely correlated with CRC metastasis and tumor stage." (PMID 28974231, 2017). "In addition, some reports have revealed involvement of CLCA1, CLCA2, and CLCA4 in tumor progression." (PMID 29190973, 2017). "Moreover, CLCA1 serum concentration and the CLCA1 mRNA expression level were inversely correlated with CRC metastasis and tumor stage." (PMID 28974231, 2017). "In addition, both CLCA1 serum concentration and CLCA1 mRNA expression level were inversely correlated with CRC metastasis and tumor stage." (PMID 28974231, 2017). "This indicates that CLCA1 may control PDT of enterocyte and therefore act as a tumour suppressor in colorectal tumorigenesis." (PMID 23593331, 2013). "Thus, it is an attractive hypothesis that CLCA1 has a role in tumor suppression in PDAC, either by interaction with tumor microenvironment or by proteolytic activation of yet undiscovered substrates." (PMID 29515771, 2018). "We also did not observe differences in the tumor volume among CL, CLCA1 and CLCA2 groups." (PMID 21811552, 2011).
cancer (22 papers, 2013 to 2025). A tumor composed of atypical neoplastic, often pleomorphic cells that invade other tissues. "Thus, better understanding of the CLCA1 phenotype in colonic epithelium and the mechanisms underlying loss of expression in carcinomas may provide a means of therapeutic intervention through reversal of progression of human colorectal carcinogenesis." (PMID 23593331, 2013). "CLCA1 is widely recognized as a gene that inhibits tumors in several cancers despite limited studies and its nascent development phase." (PMID 40690457, 2025). "According to the differential analysis results, CLCA1 expression was lower in various cancer tissues, including COAD, (P < 0.001)." (PMID 40690457, 2025). "This review summarizes the limited functional studies of CLCA1 in respiratory diseases, cancers, and gastrointestinal diseases from humans and experimental models to promote the investigation of this molecule." (PMID 31871532, 2019). "As ion channels have been suggested as emerging cancer drug targets, further investigation into the molecular mechanisms of CLCA1 in PDAC is needed." (PMID 30419838, 2018). "Combination of CLCA1 with these different accessary proteins may explain the observations from different cancers and mouse respiratory disease models that we discussed in this review." (PMID 31871532, 2019). "But the molecular mechanism how CLCA1 influences cancer cell proliferation and differentiation is still unknown." (PMID 27661117, 2016). "CLCA1, CLCA2, and CLCA4 have all been implicated in various cancers as have a number of TMEM16 proteins, and such studies could have tremendous implications for cooperative CLCA/TMEM16 roles in cancer and other diseases." (PMID 25781344, 2015). "Cancer cell subcluster 2 also expressed high levels of cell proliferation markers (TOP2A and CCND2) and a goblet cell marker (CLCA1)." (PMID 36690709, 2023). "The expression of CEBPA was decreased in cancer samples in GSE54129 dataset and formed DRLs with CLCA1, CES2." (PMID 35421923, 2022). "Except that, the probability of some differential expression genes, such as MUC2, CLCA1, REG4, and FGF3 can be used as prognostic biomarkers in NSCLC is worth exploring because they have been reported as a biomarkers in other cancers as well." (PMID 33927719, 2021). "Recent studies have shown that the expression levels of CLCA proteins, including CLCA1 and CLCA4, are abnormal in many cancer types so it may be a potential cancer predictor for patients." (PMID 35693937, 2022). "Besides CLCA1, it has also been showed that CLCA4 contributes to the progression of several types of malignant tumors including CRC." (PMID 35907803, 2022). "The positive regulation of CLCA1 and CES2 were both lost from normal to cancer, and thus may result in reduced expression of two targets, which could further inhibit proliferation or induce apoptosis." (PMID 35421923, 2022).